IFNG (interferon gamma)
Diseases named in the same sentence as IFNG in open-access papers (continued):
Sharing a sentence is not in itself a finding about the gene and the disease.
malaria (continued). "T cells co-producing IFNγ/IL-10 following nonspecific PMA/ionomycin stimulation were described in the context of acute malaria infection, and were also more abundant among children with uncomplicated rather than severe malaria, consistent with a role in modulating inflammation." (PMID 24415936, 2014).
autoimmune disease (573 papers, 2005 to 2025). A disorder resulting from loss of function or tissue destruction of an organ or multiple organs, arising from humoral or cellular immune responses of the individual to their own tissue constituents. "IFNγ expression is stringently regulated to ensure its robust but transient expression, as chronic low-level IFNγ causes autoimmune disease." (PMID 39578552, 2025). "Several studies have found an association between the rs2069705 single nucleotide polymorphism (SNP) in the IFNγ promoter and susceptibility to various autoimmune disorders." (PMID 38406824, 2024). "It is critical for innate and adaptive immunity, is encoded by IFNG, and is linked to various autoimmune diseases." (PMID 38675400, 2024). "IL-18 has been implicated in several autoimmune diseases including MS, because it stimulates γδ T cells to express IL-17 and promotes the production of the Th1 cytokine IFNγ from T cells and NK cells." (PMID 37414913, 2023). "Over the past three decades, substantial evidence has emerged to support the notion that the major pathogenic T-cell subset in autoimmune diseases produces interferon gamma (IFN-γ)." (PMID 37892114, 2023). "Aberrant IFNγ expression has been associated with a number of autoinflammatory and autoimmune diseases, including RA." (PMID 35014010, 2022). "Conversely, aberrant interferon gamma expression has been associated with a number of autoinflammatory and autoimmune diseases." (PMID 35309862, 2022). "This exploratory study aimed to evaluate T cell production of two cytokines commonly implicated in autoimmune disease, interferon-gamma (IFNg) and interleukin-17 (IL17)." (PMID 35990273, 2022). "Th17 cells, including Th17.1 cells, which have the capacity to produce IFNγ next to IL-17 or IFNγ alone, are associated with various autoimmune diseases and sarcoidosis." (PMID 34054347, 2021). "As a modest inflammatory effector, IL17 acts concertedly with other inflammatory mediators, such as TNFα and IFNγ, on pathogenic and protective processes in autoimmune disease and cancer." (PMID 32498703, 2020). "We also report a significant association of the IFNG gene SNP rs2069718 and BC in our cohort, which has been previously associated with autoimmune disease risk." (PMID 32973967, 2020). "GO annotations of the immune-related module included signalling pathway of interferon-gamma (IFNγ), a major proinflammatory cytokine implicated in CeD, is well known for its role in regulating immune responses to infections and autoimmune diseases." (PMID 33004927, 2020). "Interferon gamma (IFN-γ) is an inflammatory cytokine that associated with a number of autoimmune diseases." (PMID 32454918, 2020). "HLA-DR is an MHC class II cell surface receptor whose increased expression had been reported to be associated with autoimmune diseases and higher production of IL-1β and IFNγ upon Toll-like receptor stimulation." (PMID 32210958, 2020). "Autoimmune diseases are associated with increased Th1 and Th17 activity and increased IFNγ, which are recapitulated in the proband’s ex vivo Th cell differentiation assays." (PMID 31238969, 2019). "The direction of this effect suggests that, in contrast to its role in NTS-risk, increased STAT4 expression and IFNγ production enhances the risk of a range of autoimmune diseases." (PMID 29523850, 2018). "Recently, it was reported that naïve Th21 cells, which are implicated in autoimmune disease, do also express a combination of cytokines (IL-21 and IFNγ) typically associated with different Th cell lineages." (PMID 29973931, 2018). "Two of these clusters are highly enriched in pathways previously associated with autoimmune disease etiology (TNFα and IFNγ cytokine pathways)." (PMID 28982122, 2017). "MS was first thought to be a Th1 cell-mediated autoimmune disease, with interferon gamma (IFN-γ) assuming a pathogenic role, while Th2 cells producing primarily interleukin (IL)-4 or IL-10 exert a modulatory function with a protective role." (PMID 27491297, 2016).
autoimmune disease (continued). "Although IFNγ-producing Th17 cells have been suggested to be associated with autoimmune diseases in some studies, there is currently limited evidence that such cells can actually lead to autoimmune disease development." (PMID 26101460, 2015). "Excessive release of interferon-gamma (IFNγ) has been associated with the pathogenesis of chronic inflammatory and autoimmune diseases." (PMID 25289758, 2014). "IFNγ is a cytokine associated with a number of autoinflammatory and autoimmune diseases, due to its role in Th1 cell stimulation, differentiation, and function via STAT1 and STAT4 pathways." (PMID 24405805, 2014). "Significantly, excessive IFNγ signaling has been associated with several autoimmune diseases including systemic lupus erythematosus (SLE) in both patients and rodent models of disease." (PMID 24391643, 2013). "In one EAE mouse model autoimmune disease is enhanced in IFNγ-deficient mice as indicated by the increase of proliferating T cells in the spleen and the central nervous system." (PMID 22973278, 2012). "Several pathways related to immune response were suppressed in KPP tumors, such as pathways associated with inflammation (e.g., interferon gamma response), pathogen defense (e.g., viral myocarditis), and autoimmune diseases (e.g., systemic lupus erythematosus)." (PMID 38885192, 2024). "Also CD8-positive cells with Th17-like features and plasticity towards IFNG expression have been linked to autoimmune diseases." (PMID 36720972, 2023). "Interferon gamma (IFNγ) is a cytokine implicated in the pathogenesis of autoimmune diseases." (PMID 37213666, 2023). "However, abnormal IFNG expression is associated with many auto-inflammatory and autoimmune diseases." (PMID 36506032, 2022). "In support of this hypothesis, we found that genetic blockade of IFNγ production rescues the homeostatic defect in miR-142–deficient Treg cells and prevents development of systemic lymphoproliferative and autoimmune disorder in Foxp3CremiR-142fl/fl mice." (PMID 35180231, 2022). "Our finding is in line with emerging evidence that interferon-beta is also implicated in several autoimmune diseases, including multiple sclerosis and Alzheimer’s disease, whereas interferon signaling, particularly interferon-gamma has been shown to be associated with PTSD84,85." (PMID 30664621, 2019). "However, several studies have implicated IFNγ+ Th17 cells in the pathogenicity of autoimmune diseases." (PMID 26101460, 2015). "However, a number of other studies disagree with the notion that IFNγ-producing Th17 cells are pathogenic in autoimmune diseases." (PMID 26101460, 2015). "Aberrant IFNγ expression is associated with a number of auto-inflammatory and autoimmune diseases." (PMID 26571298, 2015). "Several human autoimmune diseases are associated with elevated production of IFNγ and IL-18." (PMID 24115947, 2013). "Furthermore, the more significant role of ΙL6 in autoimmune disease with regards to IFNγ explains the greater susceptibility of women to autoimmune disease." (PMID 23148845, 2012). "Perhaps the most convincing evidence to support a pathogenic role of IFNγ in CNS autoimmune disease was derived from an open-label, randomized clinical trial, in which 18 patients with MS received 1 μg, 30 μg, or 1000 μg of recombinant IFNγ i.v. twice a week for four weeks." (PMID 21702922, 2011). "The production of interferon-gamma (IFNgamma) in response to infection is a hallmark of innate and adaptive immunity, and its excessive release has been associated with the pathogenesis of chronic inflammatory and autoimmune diseases." (PMID 16396683, 2006). "Interestingly, CD28 also seems to play a central role in the regulation of IFNγ production, since several studies reported that CD4+ CD28- T cells secrete large amounts of IFNγ and have been associated with Th1-driven autoimmune diseases such as multiple sclerosis of rheumatoid arthritis." (PMID 35321714, 2022).
autoimmune disease (continued). "Indeed, aberrant expression of IFNγ has been associated with inflammatory and autoimmune diseases." (PMID 22925730, 2012). "Studies have shown that LDGs play a pro-inflammatory role in autoimmune diseases by inducing T cells to produce inflammatory cytokines, such as interferon-gamma (IFN-γ) and tumor necrosis factor-alpha (TNF-α)." (PMID 40689395, 2025). "The proinflammatory role of interferon-gamma (IFN-γ) is well established in autoimmune diseases and conditions characterized by intense immune activation." (PMID 41153754, 2025). "DMF, an FDA‐approved drug for autoimmune diseases, was previously shown to block IFNγ‐induced CIITA expression." (PMID 41078003, 2025). "Predictive contributions of the number of positive autoantibodies and autoimmune disease in patients with neutralizing anti-IFNγ- autoantibodies." (PMID 40313931, 2025). "Findings from previous studies indicate that IL-12 also has the ability to inhibit the development of autoimmune diseases by inducing the expression of interferon gamma (IFN-γ)." (PMID 41402737, 2025). "Interferon-gamma (IFN-γ), a type II interferon cytokine, plays a vital role in various conditions like autoimmune diseases, infectious diseases, cancer immunology, and chronic inflammatory disorders." (PMID 40940758, 2025). "IFNG has an important role in T cell mediated autoimmunity and IFNG producing T cells (i.e. Th1 cells) are known mediators in autoimmune diseases, including T1D." (PMID 40471289, 2025). "It has been reported that IFNG mediates the activated differentiation of B cells undergoing alternative extrafollicular activation in some autoimmune diseases." (PMID 40624675, 2025). "Multiple Sclerosis (MS) is an autoimmune disease characterized by autoreactive interferon gamma (IFN-γ) and interleukin (IL)-17 producing T cell-mediated inflammation, followed by neural cell demyelination." (PMID 40273120, 2025). "Interleukin-18 (IL-18), an IL-1 family cytokine with potent ability to induce interferon gamma production and enhance Th1 response, was elevated in a group of autoimmune diseases including primary Sjögren syndrome (pSS)." (PMID 40128067, 2025). "Several therapeutic approaches targeting T cell activation (i.e., Janus kinase inhibitors) and proinflammatory cytokines (i.e., antibodies against IL17, IFNγ, and TNFα) have been developed for the treatment of autoimmune disorders." (PMID 38323310, 2024). "DEGs and DASE genes were enriched for immune pathways (e.g. antigen presentation of class I MHC, interferon-gamma signaling, innate immune response, neutrophil degranulation, and interferon signaling) and autoimmune diseases." (PMID 38637586, 2024). "Studies have indicated that the expression of tumor necrosis factor-alpha (TNF-α), interferon-gamma (IFN-γ), and several interleukins (such as IL-1, IL-6, IL-12, and IL-17) is elevated in autoimmune diseases, driving inflammation and tissue damage." (PMID 39104791, 2024). "Both HT and PsA are autoimmune diseases mediated by Th1 cell immunity, with Th1 cells, interferon-gamma (IFN-γ), and the chemokine CXCL10 playing pivotal roles in their pathogenesis." (PMID 39119335, 2024). "Of note, Tregs expressing IFNγ and exhibiting reduced suppressive capacity are found in patients with autoimmune diseases such as multiple sclerosis." (PMID 37657135, 2023). "Cells that co-express IL-17A and IFNγ are more cytotoxic and potent and have been identified in a number of autoimmune diseases (43, –, 45)." (PMID 37615438, 2023). "This study investigated a possible link between PPAR-α activity, androgen levels, IFNγ production, and sex-dependent tendencies during the development of autoimmune disorders in patients with PBC and PSC." (PMID 37759496, 2023). "IL-18 also serves various functions, including IFNγ induction, NK cell activity reinforcement, cytotoxic function enhancement, and promoting inflammatory responses and autoimmune diseases." (PMID 38140264, 2023).
autoimmune disease (continued). "In certain autoimmune diseases like type 1 diabetes, multiple sclerosis, autoimmune hepatitis, and Sjogren syndrome, there is an increased frequency of IFNγ+Foxp3+ thymic Treg cells in the peripheral blood." (PMID 38259494, 2023). "Misregulation of IFNγ signaling is pervasive in disease, with too little IFNγ leading to poor infection response, too much IFNγ leading to excessive inflammation and autoimmune diseases, and dysregulation of IFNγ being important in tumor immunology." (PMID 37689116, 2023). "HT is described as a Th1-mediated autoimmune disease, and significant production of IFNγ by lymphocytes infiltrating thyroid tissues has been reported, which locally contributes to the destruction of thyroid tissues." (PMID 37663050, 2023). "LIGHT can promote the activation and proliferation of T cells to increase interferon-gamma (IFN-γ) secretion, further increasing the cytotoxicity of T lymphocytes in many autoimmune diseases." (PMID 37108160, 2023). "In more common human autoimmune diseases, defects in Treg function are accompanied with aberrant effector cytokines such as IFNγ." (PMID 37197653, 2023). "Function enrichment analysis revealed that low-expression of DLX2 was closely related to various immune-related pathways like T/B/NK cell mediated immunity, interferon gamma/alpha response, and various autoimmune disease." (PMID 36317140, 2022). "The results of function enrichment analysis showed that low-expression of DLX2 was closely related to various immune-related pathways like T/B/NK cell mediated immunity, interferon gamma/alpha response, and various autoimmune diseases." (PMID 36317140, 2022). "Previous studies demonstrated that MAC disease occurs in individuals with T-cell defects, such as those with AIDS, rare genetic or autoimmune diseases which comprise IFNγ-dependent immune responses." (PMID 36263044, 2022). "Interferon-gamma (IFN-γ) is a pro-inflammatory cytokine that plays a significant role in autoimmune diseases and inflammation." (PMID 35893855, 2022). "The pleiotropy of IFNγ functions provides a broad spectrum of biological effects ascribed to this cytokine in different autoimmune diseases and even in different stages of the same condition alternating between immunostimulatory and immunosuppressive effects." (PMID 36425763, 2022). "Accumulation of CD44+ effector T cells and heightened production of IFNγ and IL-17 also play a major role in the development of lupus-like autoimmune disease in EGR2-/-B6 mice." (PMID 35784356, 2022). "When overexpressed, IFNγ is a key factor in the pathogenesis of autoimmune diseases, uncontrolled inflammation, atherosclerosis, neurodegenerative diseases, and cancer." (PMID 34639073, 2021). "Of note, IL17A and IFNγ, two pro-inflammatory factors involved in many autoimmune disorders, were activated in NMO, MS and autoimmune GFAP astrocytopathy." (PMID 34367165, 2021). "In various autoimmune diseases such as multiple sclerosis, sarcoidosis, Crohn’s disease, and RA, IFNγ-producing Th17.1 cells are enriched at the site of inflammation and are thought to be especially pathogenic and drug resistant." (PMID 34082814, 2021). "As previously reported, beyond a certain threshold, IFNγ breaks the immune tolerance which induces autoreactive B and T cells to attack self-epitopes in specific cells and organs, leading to autoimmune diseases." (PMID 33379198, 2020). "Our data thus define a novel function for p73 in immune regulation, which affects the IFNγ response and is relevant to autoimmune disease." (PMID 32193462, 2020). "The mouse model of autoimmune diseases used here displays chronic expression of IFNγ via the genetic modification of the AU-rich element in the 3′-UTR of IFNG mRNA." (PMID 33379198, 2020). "Our data provide new insight into the mechanism of the interaction between IFNγ and leptin signaling, which furthers our understanding of the relationship between obesity and the development of Th1-mediated autoimmune diseases." (PMID 33379198, 2020).